FBXL7 (F-box and leucine rich repeat protein 7)
Diseases named in the same sentence as FBXL7 in open-access papers (continued):
Sharing a sentence is not in itself a finding about the gene and the disease.
pancreatic cancers (4 papers, 2021 to 2022). "Recently, FBXL7 promoter hypermethylation was associated with its downregulation, c-SRC induction and tumor progression in prostate and pancreatic cancers." (PMID 35887149, 2022). "Recently, FBXL7 promoter hypermethylation was associated with the FBXL7 silencing and overexpression of its target protein, c-SRC, increasing metastasis promotion in prostate and pancreatic cancers." (PMID 35887149, 2022). "The F-box and leucine-rich repeat protein 7 (FBXL7) is a potential tumor-suppressing gene, one that is frequently hypermethylated in pancreatic cancer and where the encoded protein promotes the degradation of AURKA, BIRC5 and c-SRC." (PMID 35887149, 2022). "Consistently, lower FBXL7 expression resulting from promoter hypermethylation predicts worse survival in patients with prostate and pancreatic cancers." (PMID 35906197, 2022). "The promoter of FBXL7 is hypermethylated in advanced prostate and pancreatic cancers along with decreased mRNA and protein levels of FBXL7." (PMID 35625853, 2022). "It should be noted that the promoter of FBXL7 is hypermethylated in advanced prostate and pancreatic cancers along with decreased mRNA and protein levels of FBXL7." (PMID 35625853, 2022). "Consistently, the expression level of FBXL7 is negatively correlated with the expression of c-Src in human prostate and pancreatic carcinoma tissues." (PMID 35906197, 2022). "Hypermethylation of FBXL7 promoter correlates with downregulation of FBXL7 levels and advanced tumor grade in both pancreatic carcinoma and prostate cancer." (PMID 35906197, 2022). "F-box/LRR-repeat protein 7 (FBXL7) regulates cancer metastasis and the chemosensitivity of human pancreatic cancer." (PMID 34249081, 2021). "However, FBXL7 expression both at mRNA and protein levels in pancreatic cancer specimens was further lower than that in matched tumor-adjacent tissues." (PMID 35906197, 2022). "Moreover, FBXL7 can negatively regulate pancreatic cancer cell migration and invasion via targeting Snail1 for degradation." (PMID 35906197, 2022). "Additionally, both mRNA and protein levels of FBXL7 were found to be reduced in pancreatic cancer tissues, compared to those in the corresponding tumor-adjacent normal tissues." (PMID 35906197, 2022). "In human pancreatic cancer BxPC-3 and PANC-1 cells, FBXL7 interacts with Snail1 and promotes its ubiquitylation and degradation via proteasome to suppress EMT, thereby repressing cell migration and invasion." (PMID 35906197, 2022).
Abdominal obesity (2 papers, 2020 to 2022). Excessive fat around the stomach and abdomen. "For example, one variant has been found in the NGEF gene, which has been associated with abdominal obesity, while another has been found in FBXL7, which has been associated with metabolic syndrome and with an altered pharmacological response to corticosteroids." (PMID 32872468, 2020). "Neuronal guanine nucleotide exchange factor (NGEF), with its known role linked to abdominal obesity, and F-box/LRR-repeat protein 7 (FBXL7), linked to metabolic syndrome and a modified response to corticosteroids, were among the genes found to be altered." (PMID 36551837, 2022).
lung adenocarcinoma (2 papers, 2022). A carcinoma that arises from the lung and is characterized by the presence of malignant glandular epithelial cells. "Lung adenocarcinomas (LUAD) also showed FBXL7 hypomethylation (p = 0.0494) and ever-smokers presented lower methylation levels relative to never-smokers (p = 0.0003)." (PMID 35887149, 2022). "Interestingly, compared with their corresponding normal tissues, FBXL7 expression is significantly lower in colon adenocarcinoma, lung adenocarcinoma, lung squamous cell carcinoma, and prostate adenocarcinoma, implying its potential regulation of Snail1 turnover in these specific cancer tissues." (PMID 35906197, 2022).
mastitis (2 papers, 2019 to 2021). Inflammation of breast tissue during lactation or postpartum due to an obstructed duct or infection. "The FBXL7 gene has also been reported to be located within a region that explains the highest genetic variance associated with clinical mastitis in first lactating US Holstein dairy cattle." (PMID 31311492, 2019).
prostate carcinoma (2 papers, 2022 to 2023). A carcinoma that arises from epithelial cells of the prostate gland. "Partially in line with this, low FBXL7 mRNA expression indicates poor survival in patients with pancreatic and prostatic cancers; this low expression can also facilitate the invasion of pancreatic and prostatic cancers." (PMID 37179372, 2023). "More importantly, FBXL7 depletion strikingly increased the metastasis of pancreatic and prostate cancer cells in multiple orthotopically transplanted mouse models in a manner dependent of c-SRC." (PMID 35906197, 2022). "FBXL7 knockdown promotes cell migration, invasion, and tumor metastasis via c-Src accumulation in pancreatic and advanced prostate cancers." (PMID 35906197, 2022).
allergic asthma (1 paper, 2019). A asthma with a basis in a pathological type I hypersensitivity reaction. "Namely, for environment IgE sensitization (METTL1), for allergic asthma (NTRK1), and several for FeNO (MAP3K14, NTRK1, FBXL7, PCSK6, SLC9A3, CDH26, CAPN14, and MAP3K14)." (PMID 31300640, 2019).
Barrett esophagus (1 paper, 2022). Esophageal lesion lined with columnar metaplastic epithelium which is flat or villiform. "Barrett’s esophagus cases also displayed lower FBXL7 methylation levels compared with non-tumor tissues (p = 0.0055)." (PMID 35887149, 2022). "Esophageal adenocarcinoma (EAC) cases showed FBXL7 hypomethylation relative to the non-tumor esophageal mucosa (p < 0.0001), Barrett’s esophagus (p = 0.0319) and esophageal mucosa from individuals with gastroesophageal reflux disease (GERD, p < 0.0001)." (PMID 35887149, 2022).
colorectal cancer (1 paper, 2022). A primary or metastatic malignant neoplasm that affects the colon or rectum. "Colorectal cancer was also included in this analysis, showing FBXL7 hypomethylation relative to NTST (p < 0.0001)." (PMID 35887149, 2022).
Hennekam syndrome (1 paper, 2022). Hennekam syndrome is characterized by the association of lymphoedema, intestinal lymphangiectasia, intellectual deficit and facial dysmorphism. "Indeed, homozygous deletion of exon 3 in the human FBXL7 gene encoding the F-box motif and three of the 11 LRRs, is involved in Hennekam syndrome, an autosomal recessive disorder characterized by lymphangiectasia, lymphedema, facial dysmorphism, and intellectual disability." (PMID 35906197, 2022).
Insulin resistance (1 paper, 2013). Increased resistance towards insulin, that is, diminished effectiveness of insulin in reducing blood glucose levels. "Variants of genes AKAP6, NPAS3, MARCH6 and FBXL7 have been previously reported to be associated with insulin resistance, inflammatory markers or adiposity studies using genome-wide approaches whereas associations of CDH18 and MYO10 with MetS traits have not been reported before." (PMID 23628382, 2013).
lung carcinoma (1 paper, 2022). "Overexpression of FBXL7 suppresses cell proliferation and causes apoptosis through destabilizing Aurora A and Survivin in lung cancer cells." (PMID 35906197, 2022). "Additionally, the human FBXL7 gene displays rare sporadic mutations in various carcinomas of the lung, breast, liver, stomach, pancreas, large intestine, colon, rectum, and prostate." (PMID 35906197, 2022).
myopia (1 paper, 2022). "Therefore, FBXL7 is involved in various human diseases, including asthma, atopy, Alzheimer’s disease, acute urticaria/angioedema, rheumatoid arthritis, Parkinson’s disease, chronic obstructive pulmonary disease, form-deprivation myopia, and cancer." (PMID 35906197, 2022). "Similarly, FBXL7 was also predicted to be a target of mmu-miR-1936, one of the three substantially upregulated miRNAs identified by bioinformatics analysis in mice with form-deprivation myopia, implying a potential role of FBXL7 in myopia development." (PMID 35906197, 2022).
non-small cell lung carcinoma (1 paper, 2023). A group of at least three distinct histological types of lung cancer, including non-small cell squamous cell carcinoma, adenocarcinoma, and large cell carcinoma. "F-box/LRR-repeat protein 7 (FBXL7) was predicted as a differentially expressed E3 ubiquitin ligase in non-small cell lung cancer (NSCLC), which has been suggested to influence cancer growth and metastasis." (PMID 37179372, 2023).
ovarian serous cystadenocarcinoma (1 paper, 2018). A malignant serous cystic epithelial neoplasm arising from the ovary. "Using this TCGA database, we also performed Cox univariate and multivariate analyses for age, pathologic stages, histologic grades, and FBXL7 expression in ovarian serous cystadenocarcinoma patients." (PMID 30301218, 2018). "The results showed that FBXL7 expression was positively correlated with CD44, PDGFA, PDGFC, and PDGFD in ovarian serous cystadenocarcinoma tissues with a statistical significance (p = 0.001 or p < 0.001)." (PMID 30301218, 2018). "Recent studies have shown that FBXL7 expression was positively correlated with CD44, PDGFA, PDGFC, and PDGFD in ovarian serous cystadenocarcinoma." (PMID 30301218, 2018). "Cox univariate and multivariate analyses also showed that FBXL7 upregulation and pathological stage significantly predicted a poor RFS probability after adjuvant chemotherapy in ovarian serous cystadenocarcinoma." (PMID 30301218, 2018). "In addition, FBXL7 expression was positively correlated with CD44, PDGFA, PDGFC, and PDGFD in ovarian serous cystadenocarcinoma." (PMID 30301218, 2018).
Parkinson disease (1 paper, 2022). A progressive degenerative disorder of the central nervous system characterized by loss of dopamine producing neurons in the substantia nigra and the presence of Lewy bodies in the substantia nigra and locus coeruleus. "FBXL7 mRNA levels are markedly associated with lncRNA KCNQ1OT1 predicted to target FBXL7 mRNA via hsa-miR-520g-3p based on the construction of a competing endogenous RNAs (ceRNA) network associated with Parkinson’s disease by database analysis." (PMID 35906197, 2022). "In addition, FBXL7 was identified as a hub gene involved in the pathogenesis of Parkinson’s disease, its expression being higher in the substantia nigra tissues of Parkinson’s disease, compared to that in normal controls." (PMID 35906197, 2022).
viral infection (1 paper, 2022). "Since FBXL7 hypomethylation was detected in tumors from different histologies and an association with risk-factor exposure was observed in some cases, we sought to evaluate whether this profile could also be seen in viral infection-associated HNSCC." (PMID 35887149, 2022).
tumor (13 papers, 2017 to 2025). "Notable candidate genes included ANKH (12 associated SNPs), EIF6 (11 SNPs), and SLC4A7, DLG2, and FBXL7, which are widely implicated in cellular inflammation, immune response, and tumor development." (PMID 40427243, 2025). "In OCSCC patients, FBXL7 hypomethylation was associated with an advanced tumor stage (p = 0.00923)." (PMID 35887149, 2022). "Thus, the downregulation or dysfunction of FBXL7 may cause the accumulation of substrates, promoting tumorigenesis and tumor progression." (PMID 35906197, 2022). "Overall, our study indicates that hypoxia can promote the glycolysis and tumor growth of NSCLC by regulating the EZH2/FBXL7/PFKFB4 axis." (PMID 37179372, 2023). "The findings collected from this study supported the promoting effect of hypoxia on the glucose metabolism and tumor growth of NSCLC via regulation of the EZH2/FBXL7/PFKFB4 axis." (PMID 37179372, 2023). "Taken together, knockdown of EZH2 inhibited tumor growth in vivo by mediating the FBXL7/PFKFB4 axis." (PMID 37179372, 2023). "FBXL7 gene functions are poorly understood, but the gene’s role as a tumor suppressor has been proposed based on its target proteins, AURKA, BIRC5 and c-SRC." (PMID 35887149, 2022). "More importantly, decitabine, an inhibitor of methylase, restores FBXL7 expression levels and inhibits cell migration and invasion, and tumor metastasis in an FBXL7-dependent manner." (PMID 35906197, 2022). "The high discriminatory potential of FBXL7 methylation levels between non-tumor and tumor tissues, together with the intratumor homogeneity of this molecular alteration, make it a promising biomarker." (PMID 35887149, 2022). "In this review, we summarize the downstream substrates and upstream regulators of FBXL7 and describe its aberrant expression in human cancers, with emphasis on its emerging roles in the regulation of tumorigenesis and tumor progression." (PMID 35906197, 2022). "ESCC and HNSCC have an aberrant DNA methylation profile; we show here that the FBXL7 gene body is hypomethylated in both tumor types, among other tumors of the digestive and respiratory tracts." (PMID 35887149, 2022). "FBXL7 protein positivity was generally lower in the nuclei of tumor cells, as expected by the gene body hypomethylation and the direct correlation with gene expression but was higher in the cytoplasm." (PMID 35887149, 2022). "Consistently, FBXL7 contributes to xanthohumol-mediated inhibition of OSCC xenograft tumor growth by targeting Survivin degradation." (PMID 35906197, 2022). "FBXL7 exhibits tumor-suppressive characteristics by mediating degradation of several oncogenic substrates." (PMID 35906197, 2022). "According to the direct correlation between gene body methylation and gene expression that is observed in all tumor types, decreased FBXL7 mRNA levels are likely to be detected in ESCC, LSCC, OCSCC and OPSCC, relative to their NTST." (PMID 35887149, 2022). "The expression of FBXL7 in PCa specimens was lower than that in matched tumor-adjacent tissues (n = 16, p < 0.05)." (PMID 34249081, 2021). "IHC staining was applied to assess the expression of FBXL7 in 16 pairs of PCa and tumor-adjacent tissues." (PMID 34249081, 2021). "In this study, we found that the expression of FBXL7 was down-regulated in PCa tissues compared with tumor-adjacent tissues, and the low expression of FBXL7 was positively associated with cancer metastasis." (PMID 34249081, 2021). "Here, we aimed to investigate the clinic pathologic significance of F-box proteins in PCa patients and found that FBXL7 suppressed PCa cell invasion in vitro and tumor metastasis in vivo." (PMID 34249081, 2021). "Second, in the xenograft mouse model, IHC/IF staining of Ki‐67, miR‐152‐5p levels and FBXL7 protein levels should be detected in the tumours." (PMID 32150671, 2020).
tumor (continued). "These are oncoproteins that are overexpressed in different tumor types and their targeting by FBXL7 suggests that the latter may indirectly control the cell cycle and apoptosis." (PMID 35887149, 2022). "Hence, FBXL7 plays a tumor-suppressive role in preventing tumor progression, particularly metastasis, by promoting c-SRC degradation." (PMID 35906197, 2022). "Thus, epigenetic suppression of FBXL7 by promoter methylation is an important mechanism for downregulating the expression of FBXL7, leading to tumor progression and metastasis." (PMID 35906197, 2022). "Silencing FBXL7 increases Snail1 levels and tumor metastasis in vivo." (PMID 35906197, 2022). "The discriminatory accuracy between tumors and non-tumor tissues, together with the homogeneity of FBXL7 gene body hypomethylation within the tumor mass, make it a potential diagnostic biomarker." (PMID 35887149, 2022). "These experimental results suggested that FBXL7 acts as a tumor suppressor in PCa progression." (PMID 34249081, 2021). "Therefore, we believe that FBXL7 has different regulatory functions on Snail1 in different tumor cells." (PMID 34249081, 2021). "In addition, genes such as DLG2 and FBXL7 are involved in tumor progression and immune regulation." (PMID 40427243, 2025). "In addition, knockdown of EZH2 impeded tumor growth through the FBXL7/PFKFB4 axis." (PMID 37179372, 2023). "FBXL7 promotes polyubiquitylation and degradation of diverse substrates and is involved in many biological processes, including apoptosis, cell proliferation, cell migration and invasion, tumor metastasis, DNA damage, glucose metabolism, planar cell polarity, and drug resistance." (PMID 35906197, 2022). "In conclusion, our work reveals that the EZH2/FBXL7/PFKFB4 axis plays a regulatory role in glucose metabolism and tumor growth of NSCLC, which is expected to be potential biomarkers for NSCLC." (PMID 37179372, 2023). "F-box and leucine-rich repeat protein 7 (FBXL7), an F-box protein responsible for substrate recognition by the SKP1-Cullin-1-F-box (SCF) ubiquitin ligases, plays an emerging role in the regulation of tumorigenesis and tumor progression." (PMID 35906197, 2022). "FBXL7 methylation levels did not vary according to EAC patients’ alcohol or smoking histories, which are secondary risk factors for this tumor." (PMID 35887149, 2022). "FBXL7 body methylation was positively correlated with gene expression in all evaluated tumors and lower nuclear protein staining was observed in ESCC and LSCC, relative to the non-tumor surrounding tissue." (PMID 35887149, 2022). "The high discriminatory potential of FBXL7 body hypomethylation between non-tumor and tumor tissues makes it a promising biomarker." (PMID 35887149, 2022). "FBXL7, an F-box protein that binds to substrates via SKP1-Cullin-1-F-box (SCF) E3 ubiquitin ligase, could enhance polyubiquitylation and degradation of substrates in tumor occurrence and aggression." (PMID 37180696, 2023). "Of 2,972 TUs, DE analysis retrieved 127 of Class 1 TUs significantly up-regulated in tumor specimens (adjusted P-value below 0.01, DESeq), including multiple intergenic transcripts and transcripts antisense to protein-coding genes, such as HDAC9, TPO, and FBXL7." (PMID 31732695, 2019).
cancer (9 papers, 2012 to 2024). A tumor composed of atypical neoplastic, often pleomorphic cells that invade other tissues. "The data revealed that high levels of FBXL7 transcripts predict an increased risk for cancer recurrence, with a statistical significance at log-rank p = 0.00051; HR = 1.64, p = 0.00057." (PMID 30301218, 2018). "Furthermore, some point mutations in FBXL7 that cause the inability to degrade c-Src, were identified in various human cancers." (PMID 35906197, 2022). "FBXL7 is abnormally expressed in various cancers, including ovarian, pancreatic, prostate, and brain cancers." (PMID 35906197, 2022). "FBXL7 gene body hypomethylation is common in cancers from the upper aerodigestive tract, independently of histology, with virus-associated tumors being the only exceptions." (PMID 35887149, 2022). "The locus on chr4 lies within an F-box gene, FBXL7, which plays a role in cell cycle control, and the locus surrounding chr21:34085269 comprises four protein coding genes, three of which have a role in cancer growth." (PMID 38778091, 2024). "Given the importance of dysregulation of DNA damage repair and cell cycle checkpoints as cancer hallmarks, it is plausible that FBXL7 might regulate tumorigenesis by targeting TACC2 for degradation." (PMID 35906197, 2022). "Finally, we provide future perspectives on validating FBXL7 as a cancer biomarker for diagnosis and prognosis and/or as a potential therapeutic target for anticancer treatment." (PMID 35906197, 2022). "The biological role of FBXL7 is still controversial in different types of cancers and is unknown in PCa." (PMID 34249081, 2021).